RPL14 (ribosomal protein L14)
Description:
Component of the large ribosomal subunit. The ribosome is a large ribonucleoprotein complex responsible for the synthesis of proteins in the cell.
Synonyms: L14; hRL14; RL14; CTG-B33; eL14; CAG-ISL-7
Tractability: Small molecule: an approved drug acts on it; a structure with a bound ligand is known; a high-quality ligand is known. PROTAC: UniProt records ubiquitination sites on it; ubiquitination databases record sites on it; its protein half-life has been measured; a small molecule that binds it is known. Other modalities: a drug acting on it is in phase 2 or 3 trials.
Target class: Other cytosolic protein
Gene: Protein-coding gene on chromosome 3 (40,457,292 to 40,468,587, forward strand). Ensembl gene ENSG00000188846.
Subcellular location: Cytoplasm
Subcellular location (Human Protein Atlas): Cytosol; Endoplasmic reticulum
Pathways (Reactome):
Metabolism of proteins: Eukaryotic Translation Termination; Formation of a pool of free 40S subunits; GTP hydrolysis and joining of the 60S ribosomal subunit; L13a-mediated translational silencing of Ceruloplasmin expression; PELO:HBS1L and ABCE1 dissociate a ribosome on a non-stop mRNA; Peptide chain elongation; Ribosome Quality Control (RQC) complex extracts and degrades nascent peptide; SRP-dependent cotranslational protein targeting to membrane; ZNF598 and the Ribosome-associated Quality Trigger (RQT) complex dissociate a ribosome stalled on a no-go mRNA
Metabolism of RNA: Major pathway of rRNA processing in the nucleolus and cytosol; Nonsense Mediated Decay (NMD) enhanced by the Exon Junction Complex (EJC); Nonsense Mediated Decay (NMD) independent of the Exon Junction Complex (EJC)
Cellular responses to stimuli: Response of EIF2AK4 (GCN2) to amino acid deficiency
Developmental Biology: Regulation of expression of SLITs and ROBOs
Disease: Viral mRNA Translation
Metabolism: Selenocysteine synthesis
Gene Ontology:
Molecular function: cadherin binding; protein binding; RNA binding; structural constituent of ribosome
Biological process: ribosomal large subunit biogenesis; rRNA processing; cytoplasmic translation; negative regulation of myoblast fusion; spermatogenesis; striated muscle contraction; translation
Cellular component: cytoplasm; cytosol; cytosolic large ribosomal subunit; cytosolic ribosome; endoplasmic reticulum; extracellular exosome; membrane; postsynaptic density; large ribosomal subunit; ribosome; synapse
Genetic constraint (gnomAD): Loss-of-function variants: 4 observed, 25.52 expected, observed/expected ratio (o/e) 0.16, 90% interval 0.076 to 0.36. The upper end of that interval is the gene's LOEUF score, 0.36, which puts it in group 1 of 6, group 1 being the genes least tolerant of losing a copy. Missense variants: 205 observed, 261.62 expected, observed/expected ratio (o/e) 0.78, 90% interval 0.7 to 0.88. Synonymous variants: 71 observed, 88.72 expected, observed/expected ratio (o/e) 0.8, 90% interval 0.66 to 0.98.
Homologues: Orthologues: macaque RPL14 (96% identical), pig RPL14 (89% identical), guinea pig RPL14 (87% identical), mouse Rpl14 (86% identical), rat Rpl14 (84% identical), rat Rpl14l1 (79% identical), rat Rpl14l2 (79% identical), rabbit RPL14 (67% identical), tropical clawed frog rpl14 (51% identical), zebrafish rpl14 (47% identical), Drosophila melanogaster RpL14 (33% identical), Caenorhabditis elegans rpl-14 (30% identical).
Diseases named in the same sentence as RPL14 in open-access papers:
RPL14 is named in the same sentence as 40 diseases in open-access papers, as found by Europe PMC text mining. Sharing a sentence is not in itself a finding about the gene and the disease. The quoted sentences say what the papers report.
cervical cancer (7 papers, 2021 to 2025). A primary or metastatic malignant neoplasm involving the cervix. "Previous research has linked RPL14(eL14) with esophagus squamous cell carcinomas (ESCC), lung and oral cancers, cervical cancer, colorectal cancer and glioblastoma multiforme." (PMID 34057029, 2021). "Additionally, RPL14 plays a role in the occurrence and progression of other cancers, such as esophageal squamous carcinoma, hepatocellular carcinoma, and cervical cancer." (PMID 40853920, 2025). "In addition, it has been reported that propofol inhibits cervical cancer progression by regulating the HOTAIR/miR-129-5p/RPL14 axis and HOTAIR promotes breast cancer progression by regulating the miR-129-5p/FZD7 axis." (PMID 36115953, 2022). "Propofol inhibits activation of the mammalian target of rapamycin (mTOR)/p70S6K pathway and modulates the HOTAIR/miR-129-5p/ribosomal protein L14 (RPL14) axis by decreasing HOTAIR expression, which subsequently inhibits the growth of cervical cancer cells." (PMID 40129947, 2025). "Similarly, propofol repressed the cell viability, invasion, colony formation and migration in cervical cancer cells via targeting HOTAIR and modulating miR-129-5p/RPL14 axis." (PMID 36438563, 2022). "Moreover, researches have shown that RPL14 promoted cervical cancer cell migration, invasion and EMT, which were related to cervical cancer prognosis." (PMID 33305312, 2021).
breast carcinoma (6 papers, 2012 to 2025). "Contradicting our results, previous studies have shown that low expression levels of ribosomal proteins RPS9, RPS14, RPS27, RPL11 and RPL14 are related to a poor overall survival in breast cancer patients, especially in TNBC." (PMID 37888706, 2023). "On the other hand, some down-regulated ribosomal proteins, such as RPL35A, RPL18 and RPL14 that we find in both the breast cancer tissue and cell lines have received relatively little attention and might be worth pursuing." (PMID 22346740, 2012).
viral infections (4 papers, 2020 to 2025). "RPL14 also influences immunity, as it is often disrupted during viral infections (e.g., influenza, COVID-19), where viruses hijack ribosomal proteins to replicate and evade immune defenses." (PMID 41221285, 2025).
esophageal squamous cell carcinoma (3 papers, 2021 to 2025). Esophageal squamous cell carcinoma (ESCC) is a type of esophageal carcinoma (EC) that can affect any part of the esophagus, but is usually located in the upper or middle third. "Consistent with the findings of our research, a previous study revealed that RPL14(eL14) was down-expression and could serve as an early diagnostic biomarker for esophageal squamous cell carcinomas." (PMID 34057029, 2021). "Huang found that RPL14 are frequently altered during tumorigenesis of esophageal squamous cell carcinomas (ESCC) and could be used for the early detection of ESCC." (PMID 34993140, 2021).
oral cancers (3 papers, 2006 to 2021). "Another ribosomal protein gene ectopically expressed in cancer is RPL14, transcriptional loss of which was observed in lung and oral cancers." (PMID 16608517, 2006). "Polymorphism in tumor suppressor RPL14 was associated with the pathogenesis of lung and oral cancers, but this polymorphic gene may be responsible for the growth of GBM." (PMID 31137733, 2019).
epilepsy (2 papers, 2025). A brain disorder characterized by episodes of abnormally increased neuronal discharge resulting in transient episodes of sensory or motor neurological dysfunction, or psychic dysfunction. "Among all exposure genes, RP11-267M23.4, ENTPD3-AS, ZNF619, and RPL14 were demonstrated as risk factor to epilepsy, while NBL1, RNF157, and PARP1 were protective factors to epilepsy." (PMID 40624693, 2025). "In epilepsy, mapping our m6A-associated genes (e.g., PARP1, NBL1, RPL14) to their proteomic counterparts identified causal links to proteins such as ST6GALNAC5, CTNNA2, and TOM1L1, highlighting specific m6A-driven regulatory cascades at the protein level." (PMID 40624693, 2025). "We found that RP11-267M23.4, NBL1, ENTPD3-AS, RNF157, ZNF619, RPL14, and PARP1 showed causal relationship to epilepsy." (PMID 40624693, 2025). "In the MR analysis with epilepsy as the outcome, we identified seven positive results: RP11-267M23.4, NBL1, ENTPD3-AS1, RNF157, ZNF619, RPL14, and PARP1." (PMID 40624693, 2025).
glioblastoma (2 papers, 2021). The most malignant astrocytic tumor (WHO grade IV). "In addition, RPL14 was a diagnostic markers of glioblastoma and could be used as therapeutic targets." (PMID 33305312, 2021). "However, for glioblastoma multiforme, RPL14(eL14) was upregulated and maybe accelerated the growth of tumors." (PMID 34057029, 2021).
nasopharyngeal carcinoma (2 papers, 2021). A carcinoma arising from the nasopharyngeal epithelium. "Although human/eukaryotic ribosomal protein L14 (RPL14/eL14) is known to be associated with a variety of cancers, its role in nasopharyngeal carcinoma (NPC) remains unclear." (PMID 34057029, 2021). "In addition, RPL14 may be a tumor suppressor gene in nasopharyngeal carcinoma (NPC), which could inhibit cancer progression." (PMID 34993140, 2021).
triple-negative breast carcinoma (2 papers, 2021). An invasive breast carcinoma which is negative for expression of estrogen receptor (ER), progesterone receptor (PR), and human epidermal growth factor receptor 2 (HER2). "In triple-negative breast cancer patients, the reduced expression of RPL14(eL14) was associated with lower survival rates." (PMID 34057029, 2021). "Bioinformatics analyses suggests that the low expressions of ribosomal protein L14 (RPL14) indicated poor prognosis in Triple-negative breast cancer (TNBC)." (PMID 34993140, 2021).
chronic nasopharyngitis (1 paper, 2021). "Immunohistochemical staining was utilized to test the protein expression of RPL14(eL14) in 32 chronic nasopharyngitis tissues and 86 NPC tissues." (PMID 34057029, 2021). "In the 32 chronic nasopharyngitis tissues, 53.125% exhibited high expression of RPL14(eL14) (‘-’ represents negative, ‘+’ represents positive)." (PMID 34057029, 2021).
ischemia (1 paper, 2025). A hypoperfusion of the BLOOD through an organ or tissue caused by a PATHOLOGIC CONSTRICTION or obstruction of its BLOOD VESSELS, or an absence of BLOOD CIRCULATION. "The expression of RPL10A, RPL14, RPL30, RPS18, FAU-40 (RPS30), and RPSA (Laminin Receptor, LR) was assessed in the myocardial and EAT tissues of MI, CABG and HL swine models and in LVSCs and EATDS challenged with ischemia." (PMID 39641799, 2025). "Importantly, the EATDS-derived exosomes have been unveiled for their potential cardiac responses and our previous findings identified major ribosomal proteins including RPL10A, RPL14, RPL30, RPS18, FAU-40 (RPS30), and RPSA (Laminin Receptor, LR) in the vesicles of ischemia-challenged EATDS." (PMID 39641799, 2025).
lung injury (1 paper, 2025). "Subsequent RT-qPCR analysis demonstrated that RPL14 mRNA expression remained unchanged in both lung tissue homogenates and peripheral blood neutrophils of LPS-induced acute lung injury mice." (PMID 41221285, 2025).
osteosarcoma (1 paper, 2023). A usually aggressive malignant bone-forming mesenchymal neoplasm, predominantly affecting adolescents and young adults. "In response to stress, uS3/RPS3, uS4/RPS9, uS17/RPS11, eS24/RPS24, eL6/RPL6, uL13/RPL13A, eL14/RPL14, eL30/RPL30, eL42L/RPL36AL, and RACK1 in U2OS (human osteosarcoma) cells have O-linked β-N-acetylglucosamine (O-GlcNAc) modifications." (PMID 37047306, 2023).
rheumatoid arthritis (1 paper, 2022). A chronic, systemic autoimmune disorder characterized by inflammation in the synovial membranes and articular surfaces. "Researchers implicate autoantigens, including RPL7, RPL31, RPL14, and RPL9, in the regulation of diseases such as systemic lupus erythematosus, rheumatoid arthritis, and systemic sclerosis." (PMID 35432523, 2022).
Sepsis (1 paper, 2025). Sepsis is defined as life-threatening organ dysfunction caused by a dysregulated host response to infection. "Additionally, RPL14 is linked to immune dysfunction in sepsis, a leading cause of death." (PMID 41221285, 2025).
cancer (11 papers, 2006 to 2025). A tumor composed of atypical neoplastic, often pleomorphic cells that invade other tissues. "RPL14 is a ribosomal protein, crucial for protein synthesis and often linked to cancer and developmental disorders." (PMID 40624693, 2025). "Similarly, despite very few reports regarding the association of RPL14 in cancer progression, the information regarding the extra ribosomal functions of RPL14 is largely unavailable." (PMID 39641799, 2025). "RPL14 (Ribosomal Protein L14) is essential for ribosome function and plays a role in cell growth, proliferation, and cancer progression." (PMID 41221285, 2025). "As the components of ribosome, Rps15a, Rps19, Rpl14, Rpl22 were preciously controlled by Myc and highly expressed in cancer cells, which promoted the EMT process." (PMID 34955855, 2021). "In cancer, elevated levels of RPL14 correlate with tumor growth and aggression." (PMID 41221285, 2025). "Although RPL14(eL14) has been found to be associated with a variety of cancers, the role of RPL14(eL14) in NPC remains unclear." (PMID 34057029, 2021). "In addition, two matches have been found to the mutations from the COSMIC Cancer Cell Line project, of which one pathogenic missense in the WARS protein, and one neutral insertion in RPL14." (PMID 31316139, 2019). "In conclusion, our results revealed that RPL14(eL14) may be considered as an antioncogene in NPC, which greatly suppresses cancer progression." (PMID 34057029, 2021).
tumor (9 papers, 2020 to 2025). "Ribosomal proteins RPL9 and RPL14 not only play essential roles in translation but also impact the cell cycle and apoptosis, indicating their broader implications in tumor biology." (PMID 40936684, 2025). "In an in vivo mouse model with subcutaneous injection of RPL14-expressing NPC cells, RPL14 significantly inhibited tumor growth, as evidenced by reduced tumor volume and weight." (PMID 39744943, 2025). "Among them, Rpl13, Rpl14, and Rpl18A all exist in the 60s ribosomal subunit, and previous studies have shown that they are tumor suppressor genes." (PMID 38544816, 2024). "Together, the results suggested that RPL14(eL14) may act as an antioncogene and inhibit tumor carcinogenesis in NPC." (PMID 34057029, 2021). "Furthermore, the protein expression of RPL14(eL14) was linked to NPC-related clinical pathological features, including the T and N classification of Tumor Node Metastasis (TNM) staging (all p < 0.05)." (PMID 34057029, 2021). "All these data not only indicated that the expression of RPL14(eL14) may have specific tissue heterogeneity but also effectively confirm that RPL14(eL14) may serve as an important regulator in tumor progression." (PMID 34057029, 2021). "Three of the identified proteins, RPL7a, RPL14, and RPS9, are ribosomal proteins involved in protein synthesis, control of cellular transformation, tumor growth, aggressiveness, and metastasis." (PMID 40229247, 2025). "To explore the role of RPL14 in NPC development, we conducted pathway analyses to examine the relationship between RPL14 expression and the transcriptional activity of molecular pathways in NPC tumor tissues, employing the scRNA-Seq and bulk RNA-Seq data." (PMID 39744943, 2025). "Collectively, these findings underscore RPL14 as a pivotal suppressor for EBV and tumor in NPC." (PMID 39744943, 2025). "Utilizing scRNA-Seq analysis of tumor samples from 56 NPC patients and nontumor tissues from 15 noncancerous donors, we found that RPL14 was universally expressed across all cell types, particularly malignant epithelial cells." (PMID 39744943, 2025).
RPL14 also shares sentences with these, for which no sentence is quoted: colorectal cancer (2 papers); anemia (1); anxiety disorder (1); Ataxia (1); chronic myeloid leukemia (1); COVID-19 (1); Diabetes (1); Esophageal Neoplasms (1); heart defects (1); hepatocellular carcinoma (1); immune dysfunction (1); infection (1); influenza (1); insomnia (1); liver cancer (1); lung carcinoma (1); melanoma (1); memory impairment (1); preeclampsia (1); schizophrenia (1); systemic lupus erythematosus (1); systemic sclerosis (1); tauopathies (1).